VDR (vitamin D receptor)
Diseases named in the same sentence as VDR in open-access papers (continued):
Sharing a sentence is not in itself a finding about the gene and the disease.
breast cancer (continued). "Studies have shown that miRNAs target VDR in breast carcinoma and liver fibrosis and then affect disease progression, but whether these miRNAs are differentially expressed in TB is still unclear." (PMID 36304947, 2022). "On the other hand, BRCA1 mutated breast cancer cells have been hypothesized to be sensitive to RXR and VDR modulating drugs." (PMID 33478016, 2021). "Breast cancers are highly heterogeneous, yet many express VDR, suggesting that vitamin D status may be clinically relevant for women living with this disease." (PMID 34950835, 2021). "Many scholars reported the relevance of miR-125b expression and VDR in breast cancer 3,18,19." (PMID 33390783, 2021). "As might be predicted given the heterogeneous nature of these cell lines, which were derived from different subtypes of breast cancer, only a small degree of overlap in the genes altered in response to VDR agonists was noted." (PMID 34950835, 2021). "We aimed to investigate whether SNPs in the VDR and GC gene may contribute to breast cancer relapse in patients with a family history of undefined origin." (PMID 33917614, 2021). "Expression of VDR in various tumor tissues may suggest that it has an effect on tumorigenesis, for example in breast cancer and lung cancer, and it might be related to the sex of patients." (PMID 34206371, 2021). "They found that changes in certain inflammatory biomarkers in breast cancer survivors with low plasma 25(OH)D levels, supplemented with vitamin D3, may depend on VDR SNPs and haplotypes." (PMID 33917614, 2021). "The expression of VDR in established human breast cancers suggests that its activation with natural or synthetic ligands might alter the course of the disease." (PMID 34950835, 2021). "This study assesses the role of VDR and GC SNPs on breast cancer (BC) recurrence and survival in a cohort of patients with a family history of breast cancer, without the pathogenic variant for BRCA1 and BRCA2." (PMID 33917614, 2021). "Activation and subsequent nuclear translocation of VDR upon ligand binding suggested the likelihood that 1,25D availability could affect the biology of breast cancer cells." (PMID 34950835, 2021). "However, one conclusion that can be made is that the majority of breast cancers express VDR protein at a moderate level, and a significant percentage show high VDR immunoreactivity." (PMID 34950835, 2021). "All variant distributions were in Hardy–Weinberg equilibrium in the entire genotyped cohort (p > 0.05) except VDR rs11568820, which was within expected proportions in the self-reported White cohort (p = 0.61) indicating the presence of population admixture." (PMID 34211496, 2021). "The debated influence of D3 on breast cancer proposes some answers to breast cancer statistics: as both VDR and CYP27B1 upregulate during lactation, it may be the factor contributing to positive influence of breastfeeding on breast cancer incidence." (PMID 34638264, 2021). "The relation of ER and VDR transcription is unclear: some studies show their coexpression in breast cancer samples and note their related stimulation effects, however, other studies either discovered that VDR expression induction does not cause parallel increase of ER." (PMID 34638264, 2021). "Three studies showed that VDR regulated lncRNA profiling in skin and breast cancer." (PMID 34422647, 2021). "Of note, genomic alterations in VDR were also rare (5% of cases) and the majority of these were amplifications or mRNA up-regulations, suggesting retention of vitamin D signaling in the majority of breast cancers." (PMID 32774770, 2020). "Our findings suggest that known candidate genes like FGFR2, ESR1, VDR, or BRCA2 could be associated with breast cancer in Uruguay and other admixed Latin American populations." (PMID 33126731, 2020). "Also preliminary analysis of breast cancer circulating tumor cells suggests VDR as a potential prognostic biomarker." (PMID 32257539, 2020).
breast cancer (continued). "Moreover, a positive correlation between VDR level and an inhibitor of the hedgehog pathway in breast cancer was observed." (PMID 32456160, 2020). "In addition to CRC cells, Snail1 and Snail2 also repress VDR gene expression and antagonize the antitumor action of 1,25(OH)2D3 in human osteosarcoma and breast cancer cells." (PMID 33227961, 2020). "Human breast cancer cell line MCF-7 treated with 1,25(OH)2D, similarly to different cancer models, showed an increased percentage of apoptotic cells with a cell cycle arrest in G0/G1 phase associated with an upregulation of VDR protein expression." (PMID 32560347, 2020). "Vitamin D inhibits cell proliferation via the vitamin D receptor (VDR), which may affect breast cancer risk." (PMID 32986367, 2020). "In general, VDR activation in breast cancer may result in the inhibition of the cell cycle, cell death and the induction of differentiation in breast cancer cells." (PMID 32456160, 2020). "Furthermore, Zheng and colleagues have reported that VDR overexpression in a stem cell-enriched subpopulation of MCF-7 breast cancer cells inhibits Wnt/β-catenin signaling and increases cell sensitivity to tamoxifen." (PMID 33227961, 2020). "In addition, the vitamin D receptor has been shown to modulate autophagy in normal mammary glands and luminal breast cancer cells, suggesting a potential therapeutic link between vitamin D levels and breast cancer risk." (PMID 31277291, 2019). "The present study showed a statistically significant association between BCM and VDR tumor expression among breast cancer patients (HR 0.56, 0.34–0.91), which has not been reported previously." (PMID 31358030, 2019). "Overall, our findings suggest that changes in certain inflammatory biomarkers in breast cancer survivors with low plasma 25(OH)D levels, supplemented with vitamin D3, may depend on VDR SNPs and haplotypes." (PMID 31167402, 2019). "Hence, unliganded VDR can be found on other locations in the tumor cells, and at least one other study on breast cancer survival has also found VDR in the cytoplasm along with the nuclei." (PMID 31358030, 2019). "Previous studies have not used BCM as endpoint when evaluating breast cancer prognosis, and associations found between VDR expression and different endpoints are not conclusive." (PMID 31358030, 2019). "Considering the high heterogeneity of vitamin D signaling in breast cancer, it is unknown whether vitamin D resistance through VDR methylation or CYP24A1 amplification during tumor progression would emerge for one individual’s breast cancer." (PMID 31548577, 2019). "Despite extensive research on the roles of vitamin D or VDR per se in carcinogenesis to date, no controlled trial has been performed to investigate the possible biological interactions of the VDR genetic variations with vitamin D intake on diverse aspects of the breast cancer host response." (PMID 31167402, 2019). "Compared to normal breast tissue, breast cancer lesions have been found to express more VDR." (PMID 31358030, 2019). "All of these data show that VDR and its ligand have anti-breast cancer activity." (PMID 31141879, 2019). "The VDR and vitamin D 1-hydroxylase, the enzyme that generates 1,25(OH)2D3, are expressed in the normal mouse mammary gland and human breast and1,25-dihydroxyvitamin D3 [1,25(OH)2D3] has been shown to inhibit the breast cancer cell growth." (PMID 31141879, 2019). "Also, small numbers of HER2-positive tumors and triple-negative tumors made the analyses regarding VDR expression and breast cancer mortality inconclusive." (PMID 31358030, 2019). "Moreover, the studies for an adopted vitamin D supplementation due to breast cancer focality type must be enlarged to fully comprehend the remarkable and interesting role played by the vitamin D receptor." (PMID 31731733, 2019).
breast cancer (continued). "In this study, we examined expression of AR and VDR, phosphorylation of AKT Ser473 (AKT phospho-Ser473) and ERα Ser167 (ERα phospho-Ser167), and the mutational status of the PIK3CA gene in ER-positive, HER2-negative early breast cancer tissues." (PMID 29707142, 2018). "Vitamin D supplementation, a stimulation of VDR expression, or the inhibition of Wnt/β-catenin signaling in breast CSCs might be a useful approach for the clinical treatment of breast cancers." (PMID 30314996, 2018). "However, less information is known about the inhibitory effect of vitamin D on breast cancer, and the roles played by the vitamin D receptor (VDR) and its analogs in the resistance of breast CSCs to tamoxifen." (PMID 30314996, 2018). "Moreover, DNA methyltransferase (DNMT) inhibitor induced VDR expression and enhanced the anti-proliferative effect of calcitriol in breast cancer cells." (PMID 29657326, 2018). "Whether a scenario like this may explain overexpression of VDR in BRCA1mut breast cancer cases remains to be elucidated." (PMID 28427429, 2017). "A comprehensive study on VDR in 1116 breast cancer patients revealed VDR to correlate to those clinic-pathological variables that may indicate lower tumor-biologic aggressiveness." (PMID 28427429, 2017). "Based on the known anti-proliferative function of vitamin D signaling, we hypothesized that silencing VDR expression in breast cancer cells would promote breast cancer growth." (PMID 28460457, 2017). "In the presence of adequate vitamin D, increased nuclear VDR localization and reduced unliganded VDR actions could together reduce breast cancer proliferation." (PMID 28944088, 2017). "Our mostly observational study indicates that apart from vitamin D levels, VDR status and its compartmental distribution may contribute to regulating breast cancer cell growth." (PMID 28460457, 2017). "Also, compared to NT controls, the expression of interleukin-6 (IL-6) and IL-8 mRNA was significantly reduced in breast cancer cells with disrupted VDR signaling." (PMID 28944088, 2017). "Finally, considering VDR, its higher expression has been related to better survival in patients with lung and breast cancer." (PMID 29100280, 2017). "Though several significant associations of VDR, RXR and PPARγ to clinico-pathological variables were observed in sporadic breast cancer, there was only one significant correlation detected when VDR, RXR and PPARγ were correlated to clinico-pathological variables in BRCA1mut cases." (PMID 28427429, 2017). "In line with others this suggests that VDR expression may exert differentiating effects on breast cancer cells." (PMID 28427429, 2017). "So far, no data on the prognostic significance of VDR in BRCA1 mutated breast cancer have been published." (PMID 28427429, 2017). "Further loss of both VDR and RXR predicted shortened overall survival in BRCA1mut breast cancer." (PMID 28427429, 2017). "Our results provide new mechanistic insights into showing that Ca2+-activated K+ channel KCa1.1 is a new downstream target of VDR signaling and the VDR stimulation enhanced the transcriptional repression of KCa1.1 and its protein degradation in human breast cancer cells." (PMID 27973439, 2016). "Nine articles were excluded because they did not investigate the association between VDR gene polymorphism and breast cancer risk, 2 were duplicate reports on the same study population, and 36 were not nested case-control studies." (PMID 27149457, 2016). "In the present study, we examined the effects of treatments with VD receptor (VDR) agonists on the expression and activity of KCa1.1 in human breast cancer MDA-MB-453 cells using real-time PCR, Western blotting, flow cytometry, and voltage-sensitive dye imaging." (PMID 27973439, 2016). "Several studies reported VDR-mediated responses in human breast cancer cell lines." (PMID 27973439, 2016).
breast cancer (continued). "In vitro, VDR activation in breast cancer cells reduced β-catenin activation and transcriptional activity leading to elevated expression of the extracellular Wnt inhibitor dickkopf-related protein 1, and a reduction in the interaction of β-catenin with the cyclin D1 promoter." (PMID 26008979, 2015). "Moreover, in vitro observations established a different breast cancer cell sensitivity to vitamin D treatment on the base of their VDR Cdx2 status." (PMID 25849303, 2015). "In conclusion, our data on cultured cells suggest that VDR Cdx2 status could be a marker for the use of vitamin D in the treatment on ER(–) breast cancer histotype." (PMID 25849303, 2015). "The vitamin D receptor (VDR) is a nuclear hormone receptor that protects against mammary tumor formation, progression and metastasis in the presence of 1,25D3 through induction of cell-cycle arrest, promotion of apoptosis, regulation of differentiation, and reduction in angiogenesis." (PMID 26008979, 2015). "The linkage disequilibrium (LD) pattern between the Cdx2 and other VDR polymorphisms has not been studied with respect to breast cancer risk." (PMID 25799416, 2015). "A non-significant association was observed between VDR cdx2 polymorphism and breast cancer, however the GG genotype was at risk (OR = 1.832, 95% CI = 0.695–4.828) of developing breast cancer." (PMID 25799416, 2015). "Indeed, we evaluated the VDR activity after 1α,25(OH)2D3 treatment in eight representative breast cancer cell lines." (PMID 25849303, 2015). "Therefore, VDR expression levels in breast cancer cell lines were evaluated by real-time PCR and Western blot." (PMID 25992773, 2015). "VDR-mediated signaling pathways and vitamin D levels seem to (significantly) affect the risk of several gynecological diseases, such as PCOS, endometriosis, and ovarian and even breast cancer." (PMID 26000308, 2015). "Importantly, PTPH1 is overexpressed in breast cancer and promotes breast cancer growth through increasing vitamin D receptor (VDR) cytoplasmic accumulation." (PMID 26079946, 2015). "VDR-mediated signalling pathways and vitamin D levels seem to (deeply) affect the risk of several gynaecological diseases, such as polycystic ovary syndrome (PCOS), endometriosis, and ovarian and even breast cancer." (PMID 26000308, 2015). "Over 30 years ago, the recognition that VDR expression was retained in breast cancers prompted extensive studies to determine whether targeting VDR in tumors would provide therapeutic benefit." (PMID 24982636, 2014). "Another review published in 2009 summarized the association between VDR polymorphisms and breast cancer risk, but no definitive quantitative results were obtained." (PMID 24769568, 2014). "Likewise, SV40 and RAS have been shown to reduce VDR activity in other breast cancer cell model systems." (PMID 24982636, 2014). "Calcitriol, the most active metabolite of vitamin D, elicits significant antiproliferative activity in breast cancer cells by several vitamin D receptor (VDR) mediated mechanisms including regulation of growth arrest, cell differentiation, migration, invasion and apoptosis." (PMID 24678876, 2014). "Furthermore, VDR ablation enhances the development of hyperplasias and hormone independent mammary tumors after DMBA administration, and VDR haploinsufficiency sensitizes the mammary gland to tumorigenesis driven by the neu oncogene." (PMID 24982636, 2014). "A synergistic action of 1α,25(OH)2D3 and rosiglitazone, a PPAR-γ ligand, has been shown during osteoblast-mediated mineralization, while in human T47D breast cancer cells PPAR-γ binds VDR and represses its transcriptional activity, possibly also by competing for RXR heterodimerization." (PMID 24600406, 2014). "The observation that GcMAF, a component of the vitamin D axis, exerts tumoricidal effects on human breast cancer cells through macrophage activation raises the question of whether there is any interaction between GcMAF and the VDR." (PMID 23857228, 2013).
breast cancer (continued). "However, by demonstrating similar results with a combination of low concentration of NO and 1,25D our data provide an alternative strategy for correcting corrupted VDR signaling in breast cancer cells, at least in the context of MCSCs." (PMID 23341935, 2013). "However, breast cancer cells that express functional estrogen receptor (ER+) also have high expression of VDR and display enhanced sensitivity to treatment with the active form of vitamin D (1,25-dihydroxyvitamin D, 1,25D)." (PMID 23341935, 2013). "Our findings support the thesis that the VDR gene (predisposing to melanoma and breast cancer) does not show a robust and reproducible association with the risk of psoriasis." (PMID 23805825, 2013). "Collectively, the findings suggest that dysregulation of VDR expression may contribute to the incidence and progression of breast cancer." (PMID 23304196, 2012). "In this study, we found that relationships between breast cancer risk and variants in genes associated with vitamin D activity and metabolism, VDR and CYP24A1, differed depending upon self-reported race and that associations were most notable for risk of ER- breast cancer in both AA and EA women." (PMID 22480149, 2012). "Thus, the results clearly suggest that VDR plays a crucial role in the response of MCF-7 breast cancer cells to 1α,25(OH)2D3." (PMID 23304196, 2012). "We found significant associations between breast cancer risk and a number of tag SNPs in VDR without previously known functionality." (PMID 22480149, 2012). "VDR expression has also been shown to be inversely related to breast cancer incidence." (PMID 23304196, 2012). "Immunohistochemical studies revealed that VDR expression was detectable in most analyzed B-cell Non Hodgkin Lymphoma (B-NHL) cases; however expression was at very low levels compared with normal breast tissue as well as with breast carcinoma in which VDR has been shown to be of importance." (PMID 22672495, 2012). "The majority of studies assessing polymorphisms in the VDR gene and breast cancer risk have been very small and have often failed to account for known breast cancer risk factors and potential confounders in their analyses." (PMID 18419802, 2008). "In this population-based, case-control study, none of the polymorphisms in the VDR gene were associated with postmenopausal breast cancer risk." (PMID 18419802, 2008). "Other VDR 3' SNPs or haplotypes have been inconsistently related to breast cancer." (PMID 17244366, 2007). "None of the VDR genotypes or polymorphisms in the vitamin D-binding (GC) or CYP24A1 gene was significantly associated with overall postmenopausal breast cancer risk." (PMID 17244366, 2007). "Low VDR expression and diminished vitamin D/VDR signaling are observed in breast cancer, and VDR might serve as a negative growth regulator of estrogen receptor (ER)-positive and ER-negative breast cancer cells." (PMID 37074210, 2023). "Therefore, in order to assess the expression of VDR, an immunoblotting experiment was carried out by separating the whole cell lysates of breast cancer cell lines using SDS-PAGE followed by probing the transferred proteins with specific VDR antibody, as detailed in materials and methods." (PMID 37835527, 2023). "Therefore, impaired vitamin D/VDR signaling may promote the abnormal development of the mammary gland, which may contribute to young age-onset breast cancer cases." (PMID 35328609, 2022). "In addition to proteins that are directly involved in the regulation of endocrine metabolism and growth factor production, breast cancer cells also overexpress proteins related to vitamin D metabolism and signaling via the vitamin D receptor (VDR) or calcium-sensing receptor (CaSR)." (PMID 35954312, 2022).